RNU4-65P (RNA, U4 small nuclear 65, pseudogene)
Gene: Small nuclear RNA gene on chromosome 12 (70,443,784 to 70,443,923, reverse strand). Ensembl gene ENSG00000222405.
Homologues: Orthologues: chimpanzee U4 (99% identical), dog U4 (47% identical). Paralogues in human: RNU4-31P (70% identical), RNU4-41P (68% identical), RNU4-9P (64% identical), RNU4-78P (62% identical), RNU4-52P (59% identical), RNU4-27P (58% identical), RNU4-36P (56% identical), RNU4-72P (56% identical), RNU4-75P (56% identical), RNU4-39P (54% identical), RNU4-49P (54% identical), RNU4-15P (53% identical), and 81 more.